TRPV1 (transient receptor potential cation channel subfamily V member 1)
Diseases named in the same sentence as TRPV1 in open-access papers (continued):
Sharing a sentence is not in itself a finding about the gene and the disease.
Anxiety (61 papers, 2007 to 2026). Intense feelings of nervousness, tension, or panic often arise in response to interpersonal stresses. "TRPV1-deficient mice exhibit reduced fear and anxiety; however, the effects of TRPV1 modulation in humans remain poorly understood." (PMID 41226736, 2025). "Beyond its role in pain modulation, TRPV1 activation is also implicated in regulating anxious behavior, as TRPV1-deficient mice demonstrate reduced anxiety-like behavior." (PMID 39334900, 2024). "The genotype GA of TRPV1 rs222741 was associated with increased anxiety risk as compared to the AA genotype (ORadj = 2.72, 95% CI = 1.26–5.99, p = 0.011)." (PMID 37303955, 2023). "TRPV1-deficient mice showed reduced anxiety, conditioned fear memory, and LTP in the hippocampal CA1 area." (PMID 35370565, 2022). "The Transient Receptor Potential Vanilloid type-1 (TRPV1) channel has been implicated in the modulation of seizures and anxiety-like behaviors in preclinical models." (PMID 35203625, 2022). "Here, we evaluated the effectiveness of transient receptor potential vanilloid-1 (TRPV1) blockade to alleviate ocular pain, neuroinflammation, and anxiety-like behavior associated with severe DED." (PMID 33975636, 2021). "In line with this, TRPV1-deficient mice display reduced anxiety and conditioned fear compared with their wild type littermates." (PMID 32116530, 2020). "These experiments seem to confirm that reduction of anxiety associated with analgesia produced by CBD predominantly through TRPV1 activation is mediated by 5-HT1A receptor activation." (PMID 31558911, 2019). "TRPV1 is involved in chronic pain‐related anxiety, behavioral, and associated inflammation." (PMID 41399206, 2025). "Therefore, the present results are in line with previous data and support the presence of the neuroplastic changes in TRPV1 expression underlying the comorbidity of epilepsy and anxiety in genetic and chemical models of epilepsies." (PMID 35203625, 2022). "Moreover, these TRPV1 deficient mice reportedly show impaired hippocampal-dependent learning, fear conditioning and anxiety, effects that cannot be explained by alterations in nociception." (PMID 35518644, 2022). "Growing evidence indicates that TRPV1 may be associated with the neuronal and behavioral adaptations induced by addictive drugs, including anxiety, depression, drug consumption, and drug-seeking behaviors." (PMID 29343767, 2018). "In line with this hypothesis, previous studies have shown that loss of TRPV1 channels leads to hyperactivity in juvenile mice and to decreased anxiety-related behavior." (PMID 24925072, 2014). "Moreover, it has been reported that TRPV1 receptors may participate in the modulation of emotional states, as TRPV1-deficient mice when tested in the elevated plus maze and dark-light box tasks showed less anxiety-like behavior than wild-type littermate." (PMID 28446875, 2017). "Chronic dietary capsaicin exposure—an exogenous TRPV1 agonist—has been shown to exacerbate gut microbiota dysbiosis, increase neuroinflammation, and worsen depressive- and anxiety-like behaviors in NOD mice with T1D." (PMID 41463571, 2025). "In T1D, dysregulated TRPV1 signaling contributes to cognitive decline, anxiety, altered satiety, and central autonomic failure—positioning TRPV1 as both a mechanistic link and therapeutic target in managing CNS manifestations of autoimmune diabetes." (PMID 41463571, 2025). "The TRPV1 agonist capsaicin induced anxiety‐related behaviors, while the TRPV1 antagonist AMG 9810 showed anxiolytic‐like effects." (PMID 41399206, 2025). "TRPV1 knockout mice exhibit reduced anxiety-like behaviors and impaired hippocampal long-term potentiation, indicating its role in emotional regulation and synaptic plasticity." (PMID 41463571, 2025). "In the present study, the CB1 agonist AC and the TRPV1 antagonist CZ mitigated the NC‐ and/or IM‐induced anxiety‐like behavioural alterations." (PMID 38963015, 2024).
Anxiety (continued). "Hp peptide administration induces anxiety-like behavior in rats, an effect that is mitigated by the TRPV1 channel blocker SB366791." (PMID 39334900, 2024). "Intriguingly, RVD-Hp administration counteracts the anxiety- and depressive-like behaviors induced by hemopressin, suggesting a potential blockade of the TRPV1 channel by RVD-Hp." (PMID 39334900, 2024). "On the other hand, transient receptor potential cation channel V1 (TRPV1), which plays a role in the progression of cardiac hypertrophy, temperature related anxiety, and general stress was down-regulated." (PMID 38776456, 2024). "Future studies should focus on the clinical application of RVD-Hp in treating anxiety and pain, leveraging its unique mechanism of TRPV1 channel modulation." (PMID 39334900, 2024). "Another experiment focusing on the ventral hippocampus in rats found that TRPV1 channels have an important role in regulating anxiety." (PMID 36902145, 2023). "Antagonism of TRPV1 is a possible route for the reduction in anxiety and fear responses with future translational research." (PMID 36902145, 2023). "For example, TRPV1 KO mice have shown less anxiety-related behavior, freezing, and contextual fear in different methodological designs." (PMID 36902145, 2023). "There is literature supporting TRPV1′s antagonism benefiting anxiety, and its agonism promoting protection against depression, anxiety, and substance use disorder." (PMID 36902145, 2023). "It is evidenced that TRPV1 knockout mice (TRPV1(-/-)) exhibit fewer anxiety-related behaviors on the light–dark test and elevated plus maze compared with wild-type littermates." (PMID 36364771, 2022). "We also characterized the impact of AK, a model of TLE, on anxiety-like behaviors and TRPV1 and FosB expression in the brainstem and limbic structures involved with the comorbidity epilepsy and anxiety in animals of the WAR strain." (PMID 35203625, 2022). "Here, we investigated the impact of chronic epileptic seizures in anxiety-like behavior and TRPV1 channels expression in a genetic model of epilepsy, the Wistar Audiogenic Rat (WAR) strain." (PMID 35203625, 2022). "Pharmacological manipulations of TRPV1 channels in these structures have also been shown to modulate anxiety." (PMID 35203625, 2022). "Chronic seizures increased anxiety-like behaviors and TRPV1 and FosB expression in limbic and brainstem structures involved with epilepsy and anxiety comorbidity, such as the hippocampus, superior colliculus, and periaqueductal gray matter." (PMID 35203625, 2022). "The activation of TRPV1 by the administration of agonists such as capsaicin and resinoxin to rodents elicits anxiety responses and depression-related behaviors, while antagonists induce anxiolytic and antidepressant-like effects in rodents." (PMID 36364771, 2022). "Previous studies have shown that TRPV1-/- mice exhibit learning and conditioned fear deficits as well as anxiety-like behaviors, which were related to a decrease in excitatory LTP at CA1 synapses." (PMID 34305539, 2021). "Capsazepine, an antagonist of TRPV1, exerted protective effects against psychiatric disorders such as anxiety and depression." (PMID 35052566, 2021). "Pharmacological analysis in rats revealed that the TRPV1 antagonist, capsazepine, attenuates anxiety-like behaviors in the elevated-plus maze test." (PMID 33644051, 2021). "This notion is supported by studies of TRPV1 KO mice in which show less anxiety-related behaviors, less freezing, less contextual fear and reduced LTP." (PMID 32116530, 2020). "Extensive research suggests the critical role of TRPV1 in psychological disorders such as anxiety and depression." (PMID 32774811, 2020). "Stress, anxiety, and inflammation cause changes in the expression of genes (GR, CRH, and TRPV1) in brain centers critical for stress reactivity and sensory neurotransmission (amygdala, dorsal horn)." (PMID 35295688, 2020).
Anxiety (continued). "According to recent publications, important correlations exist between genetic defects of TRPV1 and anxiety/depression, and among psychotropic drugs, capsazepine seems to have protective effects on psychiatric disorders via TRP channels." (PMID 32116530, 2020). "The pharmacological interaction between cannabinoidergic system and vanilloid type 1 (TRPV1) channels has been investigated in various conditions such as pain and anxiety." (PMID 26185513, 2015). "A few numbers of the studies have evaluated the effect of TRPV1 agonists and antagonists on anxiety-like behaviors." (PMID 23493622, 2012). "Transient receptor potential vanilloid-1 (TRPV1) channels have been reported to have a role in the modulation of anxiety-like behaviors in rodents." (PMID 23493622, 2012). "In the present study, the effects of either endocannabinoid system or TRPV1 channels and their possible interaction on anxiety-like behaviors of the rats were explored." (PMID 23493622, 2012). "TRPV1 knockout mice show reduced anxiety-related behavior and deficits in developing long-term potentiation." (PMID 19208258, 2009). "Targeting this axis and modulating it with eCBome enzyme/receptor (such as FAAH/TRPV1) blockers may have therapeutic potential in ASD-related anxiety and depressive tendencies as well as behavioral and sociability impairment." (PMID 40605060, 2025). "Moreover, several studies showed that Trpv1 deletion reduces anxiety‐related behavior in rodent models." (PMID 41399206, 2025). "In addition, cannabidiol appears to induce analgesia mainly through TRPV1, decreasing anxiety through the 5-HT1A receptor." (PMID 40430245, 2025). "These researches mainly focused on the peripheral manners, while increasing evidences discovered a new role of TRPV1 in CNS that altered gene expression related to synaptic plasticity by epigenetic regulation 94, and affected contextual fear memory, anxiety and stress-related behavior 95,96." (PMID 39816678, 2025). "Since the TRPV1 channel plays a role in pain and anxiety, antagonists and blockers of this channel might be used to treat these conditions." (PMID 39334900, 2024). "While the effects of TRPV1 on anxiety and depression may be related to cannabinoid 1 (CB1) receptor interactions and regulation of the glutamate/NMDA pathway (Lisboa and Guimarães, 2012)." (PMID 37303955, 2023). "Animal studies suggest that TRPA1 and TRPV1 antagonism might be a target for the treatment of anxiety and depression." (PMID 37303955, 2023). "Excessive activation of TRPV1 during gestation induces anxiety-like behavior in mice." (PMID 37433966, 2023). "Fetal TRPV1 activity mediates offspring anxiety-like behaviors in mice." (PMID 37433966, 2023). "Additionally, evidence supports the role of TRPV1 channels located in the brainstem and limbic structures in the modulation of emotional and anxiety-like behaviors." (PMID 35203625, 2022). "Although TRPV1 channels from neurons located in the superior colliculus have been shown to play an important role in long-term synaptic plasticity, there is still a lack of studies investigating their role on either epilepsy or anxiety." (PMID 35203625, 2022). "This may explain the activation of TRPV1 by agonists such as capsaicin and resinotoxins to induce anxiety responses and depression-related behaviors in rodents." (PMID 36364771, 2022). "Moreover, TRPV1 likely modulates anxiety, fear and panic responses in vivo and also the severity of neurological and cognitive disorders, including epilepsy, depression and Alzheimer’s Disease." (PMID 35518644, 2022). "Given the ubiquitous expression of TRPV1 throughout the brain, it is not surprising that TRPV1 has been implicated in several neurological and psychiatric disorders such as epilepsy, anxiety, and depression as well as drug-addiction disorders." (PMID 35518644, 2022). "TRPV1 is involved in the modulation of anxiety and may have implications in the treatment of depression." (PMID 34834237, 2021).
Anxiety (continued). "We here further found that TRPV1 upregulation by AAVTRPV1 could significantly ameliorate anxiety‐ and depression‐like behaviors in APP23/PS45 mice during the elevated plus maze, three‐chambered social interaction, and force swimming tests." (PMID 32061032, 2020). "Given the opposing roles of cannabinoid receptor and TRPV1 activation in regulating anxiety, novel drugs combining cannabinoid receptor agonist and TRPV1 antagonist properties may have synergistic anxiolytic effects." (PMID 31030284, 2019). "Actually, TRPV1 mediates both anxiety and emotional alterations." (PMID 28489079, 2017). "The different effect of morphine on TRPV1 mRNA level in the amygdala and hippocampus may also be explained by the different role of these regions in modulating anxiety." (PMID 24850983, 2014). "Moreover, the brain function of TRPV1 has been gradually discovered, including control of body temperature, blood pressure, emesis, locomotion, anxiety and pain modulation." (PMID 24708859, 2014). "Hippocampal TRPV1 can directly mediate synaptic plasticity and is involved in anxiety-related behaviors and conditioned fear, implying that hippocampal TRPV1 could be related to the affective or cognitive aspects of pain." (PMID 24377488, 2013). "This may give us a better deduction about the net effect of TRPV1 antagonists in the control of anxiety-like behaviors." (PMID 23493622, 2012). "Although the precise physiological role of TRPV1 in the amygdala remains unclear, functional studies in TRPV1 knockout mice demonstrated reduced anxiety-like behavior, and diminished fear conditioning and stress-sensitization, additionally implicating this receptor in emotional processing circuits." (PMID 40806746, 2025). "Moreover, TRPV1 may tonically modulate emotional defensive responses such as anxiety, fear and panic." (PMID 35518644, 2022). "The TRPV type-1 (TRPV1) is a non-selective calcium-permeable cation channel with high Ca2+ permeability that has been associated with a wide range of biological functions, such as synaptic plasticity, anxiety, fear, stress, thermoregulation, and pain." (PMID 35203625, 2022). "CBD can also exert an agonistic action on the 5-HT1a receptor that may explain its antiemetic and anxiolytic-like properties, on the GPR55 enhancing neuronal excitability, and on the TRPV1, highly localized in the hippocampus, reducing anxiety and aversive memories." (PMID 33803374, 2021). "Thus, whether CPEB3-regulated TRPV1 RNA translation exists in the brain to affect anxiety or other cognitive function remains to be determined." (PMID 26915043, 2016). "However, TRPV1−/− mice have reduced anxiety and diminished fear conditioning." (PMID 21249195, 2011). "Interestingly, TRPV1 knockout mice (TRPV1-KO) showed less anxiety-related behavior in the light-dark test and in the elevated plus-maze than their wild-type littermates as well as less freezing to a tone after auditory fear conditioning and stress sensitization." (PMID 17641734, 2007). "Preclinical studies in adult male mice demonstrate that the TRPV1 antagonist capsazepine reduces corneal sensitivity to noxious stimuli, alleviates pain, and diminishes DED-related anxiety, highlighting its therapeutic potential." (PMID 41226736, 2025). "Several studies indicate that TRPV1 and TRPV4 channel‐related neuroinflammation participates in anxiety and depression." (PMID 41399206, 2025). "Modulating this axis, through inhibitors of FAAH, TRPV1, and MAGL holds potential for sociability impairments, depression and anxiety." (PMID 40605060, 2025). "It is worth mentioning here that AEA is also known to activate transient receptor potential cation channel subfamily V member 1 (TRPV1), and mice with TRPV1 ablation exhibited decreased anxiety-like behavior." (PMID 39796008, 2024). "That is, the anxiety-reducing effect of CBD in the EPM test in lower doses disappeared with increasing doses, but was rescued by coadministration of a TRPV1 antagonist." (PMID 36239014, 2022).
Anxiety (continued). "Further evidence of TRPV1’s involvement in T1D cognitive dysfunction showed that antagonizing TRPV1 in the CA1 region of the hippocampus improved spatial learning and reduced anxiety-like behaviors in diabetic rats, suggesting that TRPV1 contributes to hippocampal overexcitation and excitotoxicity." (PMID 41463571, 2025). "The decreased density of TRPV1+ cells in the spinal cord did not rescue the anxiety-like behaviors following DMX activation." (PMID 38589429, 2024). "Because CBD activates TRPV1 and TRPV2, we hypothesize that fetal CBD exposure could disrupt brain development and affect thermal sensitivity, memory, and anxiety-like behaviors." (PMID 37433966, 2023). "Beyond CNR1, eCB system could exert actions on other targets including CNR2, transient receptor potential vanilloid receptor type 1 (TRPV1), or cyclooxygenase-2 (COX2) to participate in improvement of anxiety." (PMID 33178009, 2020). "A number of pharmacological mechanisms underpin the potential therapeutic effects of CBD generally, but its regulation of anxiety-like behaviour and learned fear processing involves 5-HT1A receptors, transient receptor potential vanilloid 1 (TRPV1) channels and endocannabinoid signalling." (PMID 31030284, 2019). "Both TRPV1- and TRPA1-KO mice showed reduced anxiety-related behaviors." (PMID 26915043, 2016). "Modulation of TRPV1 and P2RY1 receptors in animals has effects on depression and anxiety tasks." (PMID 24143878, 2013). "Furthermore, TRPV1 knockout mice have shown reduced anxiety-like behavior and impaired fear conditioning in the light-dark and EPM tests of anxiety." (PMID 23493622, 2012). "It is worth noting that Wistars (non-epileptic control rats) submitted to the AK protocol did not develop AGS, and the chronic high intense sound stimulation had no impact on anxiety or chronic neuronal hyperactivity and only a minor effect on TRPV1 expression." (PMID 35203625, 2022). "In the context of basic physiology, it has been suggested that TRPV1 also plays some roles in brain function (including nociception, thermoregulation, memory, fear, anxiety, ADHD, and epilepsy), although no brain-specific TRPV1-deficient mutants have yet been generated." (PMID 28963471, 2017). "Interestingly, CPEB3-KO mice exhibited anxiety-like responses with reduced exploratory behaviors in the open field assay, which suggests that CPEB3-suppressed TRPV1 expression may also occur in the brain." (PMID 26915043, 2016).